PIK3CA (phosphatidylinositol-4,5-bisphosphate 3-kinase catalytic subunit alpha)
Diseases named in the same sentence as PIK3CA in open-access papers (continued):
Sharing a sentence is not in itself a finding about the gene and the disease.
breast cancer (continued). "By contrast, the proliferation of IMECs and other breast cancer cell lines expressing WT PIK3CA (BT-549, MDA-MB-231, CAMA-1 and ZR-75-1) was unaffected by RNMT siRNA transfection." (PMID 30991934, 2019). "When compared with The Cancer Genome Atlas (TCGA) and Molecular Taxonomy of Breast Cancer International Consortium (METABRIC), the frequency of PIK3CA mutations was higher in KF (40.4%) than TCGA (25.0%) and METABRIC (23.8%)." (PMID 31358837, 2019). "Ongoing trials evaluating the combination of CDK4/6 inhibitors with PIK3CA agents in breast cancer [ClinicalTrials.gov June 2019]." (PMID 31396487, 2019). "Two other genes, PIK3CA and MAP 3 K1, which were selected by five scores, are also associated with breast cancer according to CGC." (PMID 30704472, 2019). "The patient who had a confirmed partial response in the PIK3CA/AKT cohort had metastatic ER+, PR-, and HER2- breast cancer with a PIK3CA E542K mutation." (PMID 31277699, 2019). "PIK3CA mRNA expression was significantly increased in breast cancer tissues compared to normal breast tissues (P<0.001, Z=5.700), also PTEN mRNA expression was significantly higher in breast carcinoma tissue compared to normal breast tissue (P<0.001, Z=5.362)." (PMID 31554385, 2019). "For example, somatic mutations in genes PIK3CA and AKT1 were identified as driver events for breast cancer, suggesting malfunction of PI3K/AKT pathway in cancer." (PMID 30682127, 2019). "Deep proteomic analyses of a large panel of breast carcinoma cell lines will be useful in identifying the full spectrum of RNMT-dependent proteins in PIK3CA-mutant breast cancer." (PMID 30991934, 2019). "Studies demonstrated that mutations in PIK3CA were more common in hormone receptor-positive and HER2-positive breast cancers." (PMID 31905960, 2019). "Comparison of the AKT1 E17K mutation and the mutation of PIK3CA displays enhanced AKT1 activity in the AKT1 mutation, but elevated activity of AKT1 and AKT2 in the PIK3CA mutated breast cancer cells." (PMID 31752925, 2019). "Our data provides in vivo validation for the synergistic effect of this combination observed in a cell-based assay and is in line with a prior study presented in an abstract form in PIK3CA mutant breast cancer xenograft models." (PMID 31217901, 2019). "Somatic mutations occurring in oncogenes PIK3CA and AKT1 have been widely reported in breast cancer." (PMID 30682127, 2019). "Nevertheless, a proportion of HER-2 amplified breast cancers continue to eventually develop drug resistance, probably due to the PTEN (phosphatase and tensin homolog) loss or activation of PIK3CA mutation." (PMID 31555586, 2019). "In our study, we confirm the presence of highly recurrent molecular alterations of the PIK3CA gene in position 1047, which likely constitute the driving genetic event in the pathogenesis of a subset of ER+/PR− breast cancers." (PMID 30691046, 2019).
breast cancer (continued). "Based on these findings, BELLE-3 was to assess the efficacy of buparlisib or placebo in combination with fulvestrant in hormone-receptor-positive, HER2-negative, advanced breast cancer patients with PIK3CA-mutant and wild-type status detected in ctDNA." (PMID 30782187, 2019). "The results corroborate a previous study showing that SGK3 is required for the growth of PIK3CA E545K mutant breast cancer cells." (PMID 30975125, 2019). "Collectively, these data indicate that breast cells harbouring oncogenic PIK3CA mutations have enhanced dependence on RNMT (mRNA cap methylation) for proliferation and survival, making RNMT a promising therapeutic target in PIK3CA mutant breast cancer." (PMID 30991934, 2019). "When we compared PIK3CA mRNA expression in breast carcinoma tissues with its expression in normal breast tissues observed significantly higher expression in carcinoma tissues than in normal tissues (P<0.001, Z=5.700)." (PMID 31554385, 2019). "Alpelisib showed some single-agent activity, with a favorable safety profile, in patients with PIK3CA-mutant advanced breast cancer." (PMID 30185228, 2018). "A previous study showed that PIK3CA-mediated breast cancer cell growth and survival are dependent on the SGK3, and Akt is dispensable." (PMID 29940988, 2018). "Their further study on 77 breast cancer cell lines reveals that BRD4 is a putative targeted option for luminal breast cancer and PIK3CA mutations probably determine the resistance to bromodomain and extra-terminal domain (BET)-inhibitors." (PMID 29753129, 2018). "The association of PIK3CA mutations with worse MFS in IBC should draw our attention to the role of the PI3K pathway in this aggressive and treatment-refractory form of breast cancer." (PMID 30086764, 2018). "Samuels and Velculescu found high frequency variations of the PIK3CA gene in breast cancer and lung cancer." (PMID 29670664, 2018). "SGK3 has been reported to be a critical effector of oncogenic PIK3CA mutant breast cancer cells in which Akt is dispensable." (PMID 29940988, 2018). "Inactivating mutations of BRCA1 and BRCA2 frequently occur in breast cancer as well, while unique mutations in GATA3, PIK3CA, and MAP3K1 are enriched in the luminal A subtype of breast cancer." (PMID 29753129, 2018). "Ribociclib also demonstrated synergistic activity in PI3K inhibitor-resistant, PIK3CA-mutant breast cancer cell lines, with the PI3K inhibitors pictilisib (GDC-0941) or alpelisib." (PMID 29789630, 2018). "Variants undetectable in locally extracted DNA of breast cancer samples were PTEN mutation (YQ/*) of BreastCa#2 at sequencing site e and PIK3CA mutation (E545K) in BreastCa#3 at sequencing site d." (PMID 29374318, 2018).
breast cancer (continued). "In postmenopausal breast cancer, we classified PIK3CA wild-type breast tumors into 4 types and PIK3CA mutant tumors into 3 types according to the phosphorylation status of AKT Ser473 and ERα Ser167." (PMID 29707142, 2018). "The most common actionable genetic alterations in the breast cancer cohort included: 8 PIK3CA (57%), 8 CDKN2A (57%), 6 FGFR (42%), 3 patients with DNA damage repair alterations (21%), and 4 PTEN (28%)." (PMID 30551737, 2018). "In the present study, we attempted to evaluate the feasibility of PTE chemotherapy for previously treated advanced HER2-positive breast cancer and to analyze QOL and biomarkers such as sHER levels, PIK3CA gene mutation status and circulating Tregs." (PMID 29599915, 2018). "Together, we successfully created an onco-genotype spectrum of PIK3CA and PIK3R1 impactful mutations, and explored their clinical associations in breast cancer." (PMID 29636477, 2018). "This was, despite the presence of PIK3CA mutations in almost 50% of premenopausal ER-positive, HER2-negative breast cancer, a frequency identical to that in postmenopausal women." (PMID 29707142, 2018). "The two remaining patients consisted of one patient with cervical cancer with a PIK3CA mutation (Glu542Lys) and another with breast cancer with both PTEN loss and PIK3CA mutation (Glu545Lys)." (PMID 32914004, 2018). "We suggest that PIK3CA is one of the key driver genes for estrogen-dependent progression in postmenopausal ER-positive early breast cancer." (PMID 29707142, 2018). "The PIK3CA gene, which encodes the p110α isoform of PI3K, is frequently mutated in more than 25% of breast cancer." (PMID 29844859, 2018). "In this study, we examined expression of AR and VDR, phosphorylation of AKT Ser473 (AKT phospho-Ser473) and ERα Ser167 (ERα phospho-Ser167), and the mutational status of the PIK3CA gene in ER-positive, HER2-negative early breast cancer tissues." (PMID 29707142, 2018). "Earlier studies have identified the PIK3CA gains in the HNSCCs, as well as in other major cancers; i.e. breast cancer, lung cancer or urothelial cancer." (PMID 29371888, 2018). "The tumor stabilization and partial tumor responses have been observed in PIK3CA mutant breast cancers treated with BKM120; meanwhile, dramatic regressions of PIK3CA mutant tumors are not typical." (PMID 29636477, 2018). "Oncogenic mutations in PIK3CA—the gene encoding the class I PI3K catalytic subunit p110α—are found in approximately one-third of human cancers and 40% of breast cancers." (PMID 29868481, 2018). "PIK3CA, which encodes the p110α catalytic subunit, is the most common genetic alteration of the AKT pathway in breast cancer, and was first demonstrated as a highly oncogenic gene in 2004." (PMID 29942710, 2018). "Here, we determine that somatic mutations in PIK3CA (44%), PIK3R1 (17%), AKT3 (15%), and PTEN (12%) are prevalent and diverse in Chinese breast cancer patients, with 60 novel mutations identified." (PMID 29636477, 2018).
breast cancer (continued). "Mutations of the phosphatidylinositol-4,-5-bisphosphate 3-kinase catalytic subunit alpha (PIK3CA) gene are one of the most frequent genetic alterations in breast cancer." (PMID 29707142, 2018). "Similar results are available for other cancer genes, such as BRAF in melanoma, BRCA1 and PIK3CA in breast cancer." (PMID 29485617, 2018). "PIK3CA amplification was occasionally observed in breast cancer, gastric cancer and esophageal squamous cell carcinoma." (PMID 28029662, 2017). "Combined CDK4/6-PI3K inhibition overcomes intrinsic and adaptive resistance leading to tumor regressions in PIK3CA mutant breast cancer PDXs." (PMID 28499452, 2017). "We observed mammary tumors at the lower end of the frequencies (range 25–100%) as reported by others in the PIK3CA‐H1047R mice." (PMID 28296140, 2017). "Over 70% of breast cancers show activation of the PI3K pathway through mechanisms such as HER2 amplification, deletion of the tumor suppressor PTEN, or oncogenic mutations in PIK3CA." (PMID 28296140, 2017). "The exception to this was PIK3CA and MAP3K1 in ER-positive tumors, in keeping with reported better relapse-free survival rates in primary breast cancers carrying PIK3CA mutations." (PMID 28810143, 2017). "PIK3CA‐H1047R mammary tumors showed strong activation of phosphorylated AKT, phosphorylated Gsk3‐β, cyclin D1, and activated β‐catenin compared to tumors from Her‐2 transgenic mice." (PMID 28296140, 2017). "To extend these findings in mouse mammary tumors to human tumor cells, we overexpressed PIK3CA‐H1047R‐ and PIK3CA‐E545K‐mutant genes in the human breast cancer cell line, HS578T." (PMID 28296140, 2017). "The phosphatidylinositol 3-kinase (PI3K) pathway is frequently activated in breast cancers due to (i) amplification of ERBB2, an oncogene that stimulates the PI3K pathway and (ii) activating mutations of the PI3K catalytic subunit, PIK3CA." (PMID 28561737, 2017). "Here we present a comprehensive network, and discrete dynamic model, of signal transduction in ER+ breast cancer based on the literature of ER+, HER2+, and PIK3CA-mutant breast cancers." (PMID 29623959, 2017). "The relationship of PIK3CA mutations and AKT activation with prognosis and treatment benefit in human breast cancer represents an area of intense investigation with mixed results." (PMID 29100327, 2017). "In breast cancer cells, increased SGK3 phosphorylation was associated with increased INPP4B expression, as well as PIK3CA and PTEN mutations." (PMID 28082369, 2017). "Berns and co-authors associated PIK3CA mutations and low PTEN expression with a reduced progression-free survival of trastuzumab-treated breast cancer patients." (PMID 27933395, 2017). "PIK3CA‐H1047R tumors expressed estrogen receptor (ER) alpha at levels similar to ER‐positive breast cancer cell lines." (PMID 28296140, 2017). "Existing large scale molecular profiling analysis notes that PIK3CA H1047R and KRAS mutations appear to coexist in genitourinary cancers and breast cancers when noted, and are less prevalent concurrently in colorectal cancer." (PMID 28781987, 2017).
breast cancer (continued). "Upstream of Stat3, Il6 tended to be highly expressed and hepatocyte growth factor (Hgf) is significantly highly expressed in mammary tumors arising in PIK3CA‐H1047R in comparison with Her‐2 transgenic mice." (PMID 28296140, 2017). "PIK3CA, encoding the p110α subunit of PI3K, harbors activating mutations in up to 45% of luminal A breast cancers, which are typically estrogen receptor (ER) positive tumors." (PMID 28476032, 2017). "Inhibitors of STAT3, β‐catenin, and IGF‐1R sensitized H1047R‐derived mouse tumor cells and PIK3CA‐H1047R overexpressing human HS578T breast cancer cells to the cytotoxic effects of PI3K inhibitors." (PMID 28296140, 2017). "BEZ235 was shown to selectively induce apoptosis in HER2-amplified and/or PIK3CA mutant breast cancer cells through inhibition of PI3K/AKT/mTORC2." (PMID 29296217, 2017). "Genetic or pharmacological inactivation of PIK3CA expression results in disappearance of mammary tumors." (PMID 29156828, 2017). "Phosphorylated Stat3 expression was higher in the mouse mammary tumors from PIK3CA‐H1047R mice in comparison with tumors from Her‐2/neu transgenic mice, as determined by IHC and western blot analysis." (PMID 28296140, 2017). "Although PI3K is downstream of Her‐2 signaling, we saw many differences between mammary tumors arising in transgenic mice overexpressing Her‐2 versus PIK3CA‐H1047R, reflecting differences observed between wild‐type and mutant PI3K." (PMID 28296140, 2017). "The luminal-type breast cancer cell lines used in our study (MCF7 and BT474 cells) had mutations in PIK3CA, whereas TNBC cell lines (MDA-MB-231 and Hs 578T cells) had wild-type PIK3CA." (PMID 29108265, 2017). "Here again, the incidence was low – 4 (13%) of 30 PIK3CA‐E545K female mice developed mammary tumors." (PMID 28296140, 2017). "PIK3CA and MUC16 mutation was frequently observed in high AR expressing breast cancer (p =.017and .013, respectively)." (PMID 28060723, 2017). "The combination of PIK3CA activating mutation and PTEN loss of function was associated with mTOR-pathway activation, most notably in the breast-cancer samples." (PMID 29137436, 2017). "Using a mouse model of HER2-overexpressing (HER2+), PIK3CA (H1047R)-mutant breast cancer, PIK3CA (H1047R) enhances HER2-mediated breast epithelial transformation and metastatic progression, which develops trastuzumab resistance." (PMID 28978097, 2017). "Coordinately, PIK3CA mutations and AKT activation by phosphorylation (pAKT) are often identified at high frequencies in breast cancer." (PMID 28388580, 2017). "Using a minimum threshold of five mutated samples (test set) and focusing initially on breast cancer, we found that MMP2 predictions were strongly associated with predictions for PIK3CA (0.47), PTEN (0.49), and AKT1 (0.28), which operate via the same pathway." (PMID 29322935, 2017). "The Wnt/β‐catenin and Stat3 pathways were activated in PIK3CA‐H1047R breast tumors and human breast cancer cell line overexpressing mutant PIK3CA." (PMID 28296140, 2017). "The PIK3CA gene encodes the p110α catalytic subunit of PI3K protein, and is mutated in over one-third of breast cancer cases." (PMID 28330468, 2017).